SNORA29 (small nucleolar RNA, H/ACA box 29)
Synonyms: ACA29
Gene: Small nucleolar RNA gene on chromosome 6 (159,785,594 to 159,785,733, reverse strand). Ensembl gene ENSG00000206910.
Gene Ontology:
Biological process: RNA processing
Cellular component: nucleolus
Homologues: Orthologues: chimpanzee SNORA29 (99% identical), macaque SNORA29 (97% identical), pig SNORA29 (89% identical), rabbit SNORA29 (83% identical), mouse Gm26130 (81% identical), rat Snora29 (81% identical), rat LOC120102642 (81% identical).